APOE (apolipoprotein E)
Diseases named in the same sentence as APOE in open-access papers (continued):
Sharing a sentence is not in itself a finding about the gene and the disease.
Cognitive impairment (continued). "We revealed in the present study through correlation and mediation analyses that ApoE ε4 can lead to cognitive impairments in T2DM patients by elevating GSK‐3β activity." (PMID 37700547, 2023). "Further longitudinal studies are necessary to better understand the role of APOE ε4 genotype in cognitive impairment and to develop specific prevention strategies for individuals at high genetic risk." (PMID 38026513, 2023). "Changes in DNM activation also occur during healthy aging as well as in populations at risk for AD, including people with mild cognitive impairment (MCI) and APOE-4 carriers." (PMID 37419975, 2023). "When examining cognitive impairment prevalence specifically in individuals who were APOE ɛ4 carriers, there was only one participant with cognitive impairment at wave 4 in group 1." (PMID 37198167, 2023). "In model 1, we evaluated the contribution of sex, race and ethnicity, years of education, and APOE*E4 status on the incidence of cognitive impairment with age." (PMID 38048131, 2023). "Another study showed that hypertensive patients with cognitive impairment carry a copy of the apolipoprotein E4 (ApoE4) gene." (PMID 36352848, 2022). "Lastly, we observed that the risk of cognitive impairment was further increased in individuals harboring both a GBA mutation and the APOE-ε4 allele." (PMID 35106798, 2022). "Although Asian populations have a lower APOE ε4 frequency (6.9%) than Europeans (10–15% in the south to 40–50% in the north), the prevalence of cognitive impairment in the Chinese population is still in a similar range to the prevalence reported in Caucasians." (PMID 35273639, 2022). "In the present study, we first examined the relationship between the enhancement of total ApoE, full‐length ApoE, and ApoE fragments and Tau phosphorylation and cognitive impairment after sevoflurane anesthesia in young (P6) and adult (P60) mice." (PMID 35810473, 2022). "We show that both APOE-ε4 and GBA mutations are risk factors for cognitive impairment, and the effect of APOE-ε4 on PDD risk is greater in early disease, which should be considered when interpreting the current literature and designing future trials." (PMID 35106798, 2022). "Selective stimulation of Abca1 with an ABCA1 agonist in mice expressing human APOE ε4, increased lipidation of ApoE ε4 and ameliorated ApoE ε4-driven cognitive impairments and brain pathology, rendering it to a similar level as the mice expressing ApoE ε3." (PMID 35477481, 2022). "Our findings further elucidate the potential of ApoE as a therapeutic target for improving cognitive impairment in aging." (PMID 36188475, 2022). "We therefore investigated the genetic effect of APOE-ε4 on body composition in older adults with mild cognitive impairment (MCI) and early-to-moderate-stage AD." (PMID 35276898, 2022). "In sensitivity analyses, when excluding all subjects with APOE ε2 and ε4 from our main age‐ and sex‐adjusted models assessing cognitive impairment (leaving subjects with APOE ε3ε3), all the statistically significant results were either weakened or annulled." (PMID 34927275, 2022). "A significant difference in apoE concentration observed between mild cognitive impairment (MCI) subjects and controls was confirmed for each apoE phenotype." (PMID 35745204, 2022). "There are several explanations for the interaction between hypertension and the APOE genotype in relation to cognitive impairment pathology." (PMID 35624902, 2022). "Although we were able to derive a possible biological mechanism linking APOE ε4, depressive symptoms, and cognitive impairment, several limitations of our analysis need to be acknowledged." (PMID 35884866, 2022). "We speculate that lifestyle-associated factors including diet might modify the APOE ε4-driven risk of neurodegeneration, especially in the light of reported beneficial effects of fish and polyunsaturated fatty acid consumption on the risk of cognitive impairment and AD." (PMID 36002891, 2022).
Cognitive impairment (continued). "To explain these findings, we investigated possible connections between depression, APOE ε4 status, and cognitive impairment." (PMID 35884866, 2022). "For example, it has been shown that genetic polymorphisms in APOE and APOC1 genes are associated with cognitive impairment progression in patients with late-onset AD." (PMID 35839250, 2022). "It is well known that high-fat and high-free-sugar diets are part of the environmental factors that can aggravate or favor the development of anxiety; many reports have shown that a high-fat diet accelerates cognitive deficits and anxiety in ApoE−/− mice." (PMID 36077225, 2022). "Our data imply that APOE ε4 expands the FC alteration, which is related to the cognitive impairment pattern in hypertensive patients." (PMID 35624902, 2022). "Genetic studies have previously identified individual markers, especially for GBA and APOE, in PD cognitive impairment progression, but markers for motor progression have been elusive." (PMID 36302787, 2022). "In our analysis, we identified hsa-miR-107 as a possible biological link between APOE ε4, depressive symptoms, and cognitive impairment." (PMID 35884866, 2022). "Hazard ratios and confidence intervals for moderate cognitive impairment across levels of alcohol intake at midlife by APOE ε4 status." (PMID 35275952, 2022). "Studies have shown that structural and metabolic parameters of the brain decline at relatively younger ages in HIV-1-infected apolipoprotein E4 (ApoE4) carriers, leading to cognitive deficit and inflammation." (PMID 36680084, 2022). "APOE ε4 allele distribution and association with SCD-Q9 scores were calculated and the effects on cognitive impairment were analyzed." (PMID 35720695, 2022). "Women between the ages of 65 and 75 with APOE ε3/ε4 have an increased risk of developing mild cognitive impairment (MCI) or AD compared with men, and the association between APOE ε4 and cerebrospinal fluid (CSF) tau level is stronger among women than men." (PMID 33746700, 2021). "Cumulatively, ABCA1-mediated ApoE lipidation is thought to be necessary for the efficient clearance of Aβ and the improvement of cognitive impairment." (PMID 34045954, 2021). "We suspected that the APOE ε2 gene showed the protective effect after the appearance of cognitive impairment." (PMID 33994988, 2021). "The presence of the APOE-ε4 is related to increased atrophy of crucial brains’ structures and cognitive impairment." (PMID 34300173, 2021). "A previous study found that urinary AD7c-NTP levels were significantly elevated in patients with mild cognitive impairment (MCI) with the APOE ε4 genotype." (PMID 34660786, 2021). "Considering the APOE ε4 genotype as a covariate, we found that plasma p-tau181 has an independent and significant contribution to the prediction of AD in patients with cognitive impairment." (PMID 33766131, 2021). "However, the association between ApoE ε4 polymorphism and the presence of cognitive impairment has been inconsistent in various populations around the world and whether the cause-effect association of the presence of CVRF and MCI is modulated by the ApoE ε4 polymorphism is also unclear." (PMID 33430178, 2021). "Several of these factors—CSVD markers, CSS, and APOE genotypes—are also indicative of CAA, which has been associated to cognitive impairment and should be considered a condition of interest." (PMID 34512528, 2021). "The applied assumption of monotonic directionality was a reflection of the biology of the AD subtypes observed when examining demographic and clinicopathologic differences (e.g., age, sex, APOE, cognitive impairment)." (PMID 33875655, 2021). "Previous studies in this area have observed that those with the APOE-ε4+ genotype tend to accumulate higher amyloid loads than APOE-ε4–, at all ages and at all cognitive impairment levels." (PMID 34305574, 2021).
Cognitive impairment (continued). "The study reported that the homozygous ε4 carriers have lower serum HDL with positively concordant cognitive impairments, showing that the APOE isoforms play major roles in serum lipid levels and the assessments of cognitive impairments and memory." (PMID 35071357, 2021). "Daily treatment with 40 IU insulin modulated cognition for adults with AD or mild cognitive impairment, with the apolipoprotein E-related differences in treatment response for the primary memory composite." (PMID 34108878, 2021). "In APOE ε4 carriers, low serum HDL-c levels were positively associated with cognitive impairment, and participants with higher HDL levels had higher MMSE scores." (PMID 32231559, 2020). "MCI and AD patients had lower brain and hippocampal volumes, greater cognitive impairment, and were more likely to be an APOE ε4 carrier than controls." (PMID 32587882, 2020). "Additionally, we found APOE ε4 allele could accelerate the age-related reductions in the attention, executive function and language ability, which are main impaired cognitive domains in mild cognitive impairment and early stage of AD." (PMID 32572010, 2020). "After adjustment for age, sex, educational level, and APOE ε4 genotype, only CSF Ng showed the ability to predict cognitive impairment." (PMID 32421689, 2020). "It has further been shown that CS-6253 improved APOE lipidation, reduced amyloid and tau pathology, and mitigated APOE4-driven cognitive impairment in mice." (PMID 32899606, 2020). "The aim of this study was to investigate the APOE genotype-dependent relationship between peripheral serum lipid levels and cognitive impairment." (PMID 32231559, 2020). "Compared to APOE non-ε4 carriers, the ε4 carriers had a 15% higher odds of cognitive impairment (OR: 1.15, 95% CI: 1.05, 1.26)." (PMID 31919381, 2020). "Previous studies have confirmed that ApoE ɛ4 prevalence is 51% in the cognitively normal population, 64% in patients with mild cognitive impairment, and 66% in patients with AD." (PMID 32587611, 2020). "Mild cognitive impairment was present in 16% at enrollment, and 27% of subjects were APOE ε4 positive." (PMID 33948250, 2020). "Although hyperconnectivity has been mainly identified in functional networks, higher binary structural network properties were also described in APOE-ε4 carriers before mild cognitive impairment (MCI) appears." (PMID 32537533, 2020). "Since one year increase in age has a 6% increased odds of cognitive impairment (OR: 1.06, 95% CI: 1.06, 1.07) in our model, the effect of APOE ε4 carriers was equivalent to 2.5 additional years of aging." (PMID 31919381, 2020). "The APOE4/4 genotype is associated with a 30–55% risk of developing mild cognitive impairment (MCI) or AD by age 85, compared to a 10–15% risk for the APOE 3/3 genotype." (PMID 31920610, 2019). "Here, we selected patients with cognitive impairment and high levels of both Aβ plaques and Tau tangles as representative cases of AD and studied Aβ and Apolipoprotein E (ApoE) expression in their brain." (PMID 30850702, 2019). "The aim of this study was to evaluate neurobiological effects of the APOE-genotype on the pattern of the structural covariance in mild cognitive impairment (MCI) subjects." (PMID 31920926, 2019). "This study sought to investigate the influence of APOE genotype on cognition and neuroimaging features in cognitively normal (CN) elderly individuals and patients with mild cognitive impairment (MCI)." (PMID 32226373, 2019). "It seems that the polymorphic poly-T variant in the TOMM40 gene provides greatly improved accuracy in the estimation of cognitive disorders for APOE ε3 carriers." (PMID 31760383, 2019). "In the last few decades, many studies investigated the impact of APOE genotype variations on brain structure and function in individuals with AD or mild cognitive impairment (MCI) and healthy elders using neuroimaging and genetic analysis." (PMID 32226373, 2019).
Cognitive impairment (continued). "A well-known AD risk factor, the apolipoprotein E epsilon 4 (APOE-ε4) allele, confers a higher risk of converting from mild cognitive impairment (MCI) to AD on female patients compared to males." (PMID 29988365, 2018). "Collectively, BSSM treatment leads to cognitive impairment of spatial learning and memory in ApoE-KO mice with western type diet." (PMID 30337867, 2018). "This study aimed at evaluating interactions between APOE-ε4 and RNF219/G variants in the modulation of behavioral and cognitive features of two cohorts of patients suffering from mild cognitive impairment (MCI) or AD." (PMID 29755337, 2018). "There were two studies regarding the effects of ApoE status on components in auditory oddball paradigms in mild cognitive impairment patients." (PMID 30186155, 2018). "The administrations of retinoid X receptor (RXR) agonist, bexarotene, was shown to increase APOE level and its lipidation resulting in a reversal of cognitive deficits observed in APP mouse models." (PMID 30587772, 2018). "To investigate whether P2X7R and APOE polymorphisms impact on long-term mortality in a cohort of older patients with acute HF, and to evaluate their association with concurrent morbidities worsening their prognosis, like cognitive impairment, we designed the present study." (PMID 28840058, 2017). "AD mouse models expressing human APOE isoforms to a large extent recapitulate amyloid phenotype and cognitive deficits." (PMID 28241068, 2017). "Lipidomic analyses were also performed on blood from an AD mouse model expressing human APOE isoforms (EFAD) and five AD mutations and from 195 cognitively normal participants, 23 of who converted to mild cognitive impairment (MCI)/AD within 3 years." (PMID 28333036, 2017). "ABCA1 has a potential role in the progress of cognitive impairment; a deficiency in ABCA1 reduces the brain APOE but increases the Aβ levels." (PMID 28824418, 2017). "This idea is in line with evidence showing that apolipoprotein E genotype and cerebrovascular pathology such as poor CVR and carotid artery intima-media thickness (IMT) can increase the risk of conversion from mild cognitive impairment (MCI) to AD." (PMID 28234912, 2017). "In particular, as early cognitive deficits and hippocampal cholinergic dysfunction were evident only in the presence of both EAE associated neuroinflammation and APOE-KO/APOE4 knock-in, a two-hit mechanism has been proposed." (PMID 29209169, 2017). "Genetic factors are involved in diabetes and AD cognitive impairment such as apolipoprotein E (ApoE)." (PMID 28890694, 2017). "Scientists have reported cognitive impairment in ApoE knockout (ApoE-KO) mice, with cholinergic deficits, decreased synaptic excitability, amyloid-β (Aβ) deposition, and impaired function of synaptosomes." (PMID 27965573, 2016). "The two methods for age correction gave similar results and show that age can partially masks the influence of other aspects such as cognitive impairment, ApoE-e4 genotype and gender." (PMID 26440606, 2016). "Consistent with our predictions, a higher genetic risk score significantly predicted a higher risk of having cognitive impairment (OR = 3.824, P = .013, and 95% C.I. = 1.333, 10.973) when controlling individual polymorphisms in BDNF, COMT, and APOE." (PMID 26366299, 2015). "ApoE levels were then analysed between clinical classifications (healthy controls, mild cognitive impairment (MCI) and AD) and correlated with the data available from the AIBL cohort, including but not limited to APOE genotype and cerebral amyloid burden." (PMID 25859282, 2015). "We also assess the relationship between cognitive impairment and factors such as years of education, APOE gene, co-morbidities and lifestyle variables." (PMID 24736378, 2014). "Previous neuropsychological studies have shown that patients with AD and mild cognitive impairment (MCI) who are APOE ε4 carriers perform worse on memory tasks." (PMID 24914687, 2014).
Cognitive impairment (continued). "Intracerebral administration of thrombin to rodents increases apolipoprotein E levels and results in neuronal injury and cognitive deficits." (PMID 23675346, 2013). "With regard to cognitive disorders, we have used this platform to explain the differential clinical effect of memantine and apolipoprotein E (APOE) on ADAS-Cog in Alzheimer patients." (PMID 23596419, 2013). "The most consistently reported factors are the presence of the apolipoprotein-E (APOE) ε4 allele, a diagnosis of mild cognitive impairment (MCI), and impaired glucose tolerance and type 2 diabetes mellitus." (PMID 24961307, 2013). "As an independent validation, we reproduced clinical data for apolipoprotein E (APOE) genotypes showing that the ApoE4 genotype reduces the network performance much more in mild cognitive impairment conditions than at later stages of AD pathology." (PMID 23181523, 2012). "Human apoE-Tg mouse models demonstrate that, compared to apoE3, apoE4 increases markers of neurodegeneration and cognitive impairment." (PMID 22028984, 2011). "In our previous study, mouse MSCs (mMSCs) were implanted into the brains of ApoE null mice, resulting in production of small amounts of ApoE in the brain and attenuation of cognitive deficits." (PMID 18823563, 2008). "Levels of ApoE in CSF are correlated with tau and 24S-hydroxycholesterol in patients with cognitive disorders." (PMID 18363842, 2008). "As ApoE null mice mature, the animals develop cognitive impairment, but upon behavioural analysis, the presence of mMSCs resulted in improved cognitive behavioural testing compared to the control groups." (PMID 18823563, 2008). "Taken together, these results suggest that disturbances in brain glucose metabolism and/or insulin signaling induced by APOE isoforms may be key to understanding the mechanisms of neurodegenerative changes in individuals with cognitive impairment." (PMID 39814004, 2025). "This aligns with previous research showing that individuals with the APOE-ε4 allele experience accelerated motor decline independent of detectable cognitive impairment." (PMID 41479611, 2025). "Second, the complex dependencies among APOE variation, cognitive impairment, and NPS mean that our result may be specific to the population, setting and model formulation used." (PMID 39974048, 2025). "The convergence of genetic susceptibility and environmental exposures, such as the APOE gene and the Amyloid Precursor Protein (APP), along with lifestyle and nutritional status, further complicates the relationship between sarcopenia and cognitive disorders." (PMID 40435122, 2025). "Research has confirmed73that different APOE alleles have different functions in lipid metabolism, which leads to varying effects on neuroinflammation and lipoprotein composition; therefore, APOE, especially APOE4, is widely considered to be associated with an increased risk of cognitive impairments." (PMID 39814004, 2025). "Clinical trials have suggested that different types of the KD significantly improve the quality of life and daily function and eased AD-related cognitive impairment, especially in individuals without the epsilon 4 allele of the apolipoprotein E gene (APOE ɛ4)." (PMID 40034740, 2025). "While accumulating studies have evaluated the interaction between PA and APOE ε4 genotype on cognitive impairment risk, results remain contradictory, with some reporting evidence of APOE-PA interaction and others not." (PMID 39789564, 2025). "Seventh, due to the limited sample size, our logistic regression analysis using a single categorical variable (four groups with APOE ε4 and seizure frequency combination) on cognitive impairment may reduce the statistical power of our findings." (PMID 40405274, 2025). "Furthermore, the allele was associated with a quicker decline in entorhinal cortex thickness and worse memory function in people with mild cognitive impairment or AD who carry the APOE E4 gene." (PMID 40360788, 2025).